RN7SL464P (RNA, 7SL, cytoplasmic 464, pseudogene)
Gene: Miscellaneous RNA gene on chromosome 1 (220,571,739 to 220,572,035, reverse strand). Ensembl gene ENSG00000243872.
Homologues: Orthologues: chimpanzee Metazoa_SRP (99% identical), macaque Metazoa_SRP (94% identical), guinea pig Metazoa_SRP (84% identical). Paralogues in human: RN7SL2 (86% identical), RN7SL1 (85% identical), RN7SL3 (85% identical), RN7SL665P (84% identical), RN7SL607P (83% identical), RN7SL664P (82% identical), RN7SL709P (82% identical), RN7SL20P (81% identical), RN7SL230P (81% identical), RN7SL769P (81% identical), RN7SL91P (81% identical), RN7SL126P (81% identical), and 704 more.